CCL7 (C-C motif chemokine ligand 7)
Diseases named in the same sentence as CCL7 in open-access papers (continued):
Sharing a sentence is not in itself a finding about the gene and the disease.
infection (continued). "For monocytes, this suggests that about 70% of the infiltration in response to TMEV infection is dependent upon the CCL2:CCR2 axis and about 30% requires the CCL7:CCR2 axis." (PMID 29202854, 2017). "Further, although we did not observe significant differences in monocyte recruitment to the footpad, CCL3, CCL4, CCL7, and CXCL10 are all known monocyte chemoattractants that were also significantly reduced during Opal524R infection." (PMID 29138302, 2017). "Three notable exceptions were CCL7, CXCL10 and CXCL11, which peaked (respectively) at 42.8, 35.5 and 6.6 times the level of expression at 7 days post-infection compared to the pre-infection levels." (PMID 27595844, 2016). "Among these, some became upregulated during the early stage of infection (day 4) CCL7, CXCL11, IL1R1 (cytokine receptor) and IL15RA, and others became upregulated during the late stage of infection (day 7): IL2RA, CSF2RB and others." (PMID 27595844, 2016). "Thirteen days after infection, mRNA expression of CCL3 and CCL7 in the spleens of MyD88−/− was increased by approximately 21 and 61 fold respectively over non-infected MyD88−/−." (PMID 23374751, 2013). "Recruitment of inflammatory monocytes to the site of infection, that is driven by the chemokines MCP1 (CCL2) and MCP3 (CCL7), is an important mechanism supporting development of innate immunity against L. monocytogenes infection." (PMID 22629382, 2012). "CCL2, CCL7, and CCL8, members of the chemokine family, recruit monocytes to sites of injury and infection." (PMID 16805906, 2006). "Lastly, exclusive expression of many genes encoding immune mediators, which allocate to signaling by interleukins or chemokines could be detected in male-derived macrophages upon infection at 6 hpi, such as CXCL1, IL32, CCL7 and IL1B." (PMID 40794782, 2025). "Similarly, the expression levels of pro-inflammatory response factors (IL-6, TNF-α, CXCL10, CCL7, CXCL11, and CCL2) were significantly decreased at 6 dpi, as compared to virulent WT infection." (PMID 37623322, 2023). "Infection with both ZIKV lineages was characterized by a more proinflammatory and chemotactic profile, mediated by high levels of IL-1β, IL-6, TNF-α, CCL-2, CCL-3, CCL-7, CXCL8, IP-10, and VEGF." (PMID 37227282, 2023). "In this setting, TAT-I24 significantly reduced the transcript levels of Ccl7, Cxcl10 and Ccl5 2 h post-infection, indicating that the inhibitory effect of the peptide is not linked to the reduction of viral gene expression." (PMID 35806257, 2022). "Surprisingly, mice that were deficient in MCP-1/CCL2, MCP-3/CCL7, and MCP-5/CCL12, individually or collectively, were not nearly as susceptible to ID LVS infection as CCR2 KO mice." (PMID 33760886, 2021). "Furthermore, the top six DEGs, including CSF3, CCL2, CCL7, IL6, CXCL11, and CXCL10, were all upregulated after infection at P3." (PMID 34026883, 2021). "TNF-α, IL-6, CXCL1, CCL2, and CCL7 levels significantly increased in the sera of klotho WT and KO mice at 1 day post-infection, while the level of IL-12 was not." (PMID 33329595, 2020). "In fact, results from a recent study demonstrated that peripheral infection with WNV increased CNS expression of chemokines important for lymphocyte trafficking, including CCL2, CCL7, CXCL9, and CXCL10, in PLX5622-treated mice compared with control-treated mice." (PMID 30704498, 2019). "The enhanced dermal inflammation early in infection in the absence of CCL7 was characterized by elevated neutrophils, IL-4, and IL-17." (PMID 30671055, 2018). "When the infection was mostly cleared in WT mice (day 9), we observed a decrease in most chemokines, but not in IL-1α and IL-1β, CCL7, and CCL4." (PMID 30102746, 2018). "We first choose to measure the mRNA levels for iNOS, a gene that is transcribed in vivo by cardiomyocytes in response to LPS inoculation, as well as those for CCL5, CCL7 and CXCL10, three chemokines transcribed in newborn cardiomyocytes after in vitro infection with T. cruzi." (PMID 30067739, 2018).
infection (continued). "By nanoString and real-time PCR profiling of the host response to the various mutants, we found that infection with the ΔgliP mutant enhanced expression of multiple chemokines, including CXCL2, CCL3, CCL4, and CCL7, which recruit neutrophils and macrophages to sites of inflammation." (PMID 30052103, 2018). "We therefore examined gene expression for several important interferon-related genes (IFNα2, IFNα4, IFNβ, IFNαβR, IFNγ, IFNγR, Irf3, Irf7, Mx1, Oas1, IFITM1, IFITM2), along with inflammasome-related genes IL-1β and NLRP3, and chemokines CCL5, CCL7, and CCL12 at d1 post-infection." (PMID 26110868, 2015). "Except for CCL7, there was no upregulation of mRNA expression of chemokines after infection in both MyD88−/− and MyD88+/+ mice." (PMID 23374751, 2013). "However, at later stages of infection, IFNs-I become central mediators of CCL2/CCL7 production and monocyte egression." (PMID 22911155, 2012). "The expression of 277 genes was induced >2-fold in a statistically significant manner by infection with Mtb:Δ-sigH at the 0 hr time-point Some of the genes with the greatest induction included CCL4 (17.6-fold), CXCL2 (10-fold), CCL7 (6.5-fold) and CCL20 (4.3-fold)." (PMID 22235255, 2012). "Furthermore, the MCPs including CCL2, CCL7, CCL8, and CCL12, which were evaluated in a few studies, might be useful biomarkers to distinguish the infection stages of this disease." (PMID 28752079, 2017). "In addition, B. dermatitidis DppIVA, which is a multifunctional protein that can act as a serine protease, assists in evasion of the host immune response during infection by cleaving CCL7, a C-C chemokine signal, which recruits Ly6Chi CCR2+ monocytes to the sites of infection." (PMID 27896220, 2016). "The mouse data suggest that CCL7 blockade may be a useful therapeutic strategy to reduce the infiltration of inflammatory cells into the kidneys, thereby improving AKI, without affecting the systemic mobilization of bone marrow cells, which may contribute to the defense against infection." (PMID 38022595, 2023). "Surprisingly, the chemokines responsible for susceptibility could not be identified either individually or in combination: mice deficient in MCP-1/CCL2, MCP-3/CCL7 KO mice, or MCP-5/CCL12, the major known murine ligands for CCR2, were not unusually susceptible following ID LVS infection." (PMID 33760886, 2021). "Infection of MDMs with non-opsonized bacilli induced, at least 10-fold, the synthesis of most tested cytokines except IL-15, IL-27, CCL2 and CCL7." (PMID 37781389, 2023). "Nonetheless, at this LVS infection dose, mice lacking circulating MCP-1/CCL2, MCP-3/CCL7, and MCP-5/CCL12 largely survived, while CCR2 KO mice did not." (PMID 33760886, 2021). "Of the 21 analytes that were evaluated, 9 analytes (angiopoietin, CCL3, CCL5, CCL7, CCL12, CXCL10, and TNF-α) were significantly changed in response to infection in both non-pregnant and pregnant mice, and more robust response was, in general, noted in non-pregnant mice (p < 0.05)." (PMID 38104118, 2023). "Cytokine signaling of IL-1β, IL-23, IL-17A, CCL7, CXCL10, TRAIL, CD40L, and BAFF provides protection against acute WNV infection in mice; IL-10 and IL-22 aid in WNV pathogenicity; IL-6 and IL-12 had no apparent effect during infection; and CCL2, TNF-α, and FasL roles remain elusive." (PMID 36992514, 2023). "However, downregulation of host genes such as Ccl7, Ccl5 and Cxcl10 by TAT-I24 at early time-points of infection could not be reversed when infection was performed with UV-irradiated MCMV, which was not able to induce viral gene expression due to severely damaged DNA." (PMID 35806257, 2022).
cancer (86 papers, 2012 to 2025). A tumor composed of atypical neoplastic, often pleomorphic cells that invade other tissues. "A positive correlation was recognized between SLC2A1 expression and chemokines in numerous cancer types, with CCL7/26 and CXCL8 being primarily associated with LUAD." (PMID 40824962, 2025). "Chemokine (C‐C motif) ligand 7 (CCL7), a chemokine protein, has been implicated in the progression of various cancers." (PMID 40062588, 2025). "Using single cell RNA-sequencing, we observed expression of CCL8, CXCL5, CCL13 and CCL7 in cancer-associated fibroblasts (CAFs)." (PMID 39249543, 2024). "It has already been confirmed that CAFs (Cancer-Associated Fibroblasts) are characterized by increased production of CCL7, as also shown in our research." (PMID 36012171, 2022). "CCL7 has reportedly been highly expressed in advanced cancers and linked to the more aggressive malignant phenotype of cancer cells such as survival, proliferation, EMT, invasion, and metastasis." (PMID 36118415, 2022). "CCL7, a chemokine that attracts various leukocytes, has been implicated in some immune disorders, and a potential role of CCL7 in cancer has been suggested." (PMID 34206004, 2021). "In CRC, overexpression of CCL7 was also associated with cancer proliferation, invasion, and migration in vitro and in vivo." (PMID 33175885, 2020). "For example, CCL7 (rho=0.357, p=0) is derived from cancer-associated fibroblasts (CAFs) in the interstitial microenvironment." (PMID 31400751, 2019). "The strong effects of fibroblast CCL7 appeared to be caused by a significant effect on cancer cell proliferation, which was unique among the factors tested." (PMID 24068959, 2013). "Furthermore, cytokines Ccl2, Ccl4, Ccl7, Ccl22, and Il21r, which associated with an M2-like, pro-cancer macrophage phenotype, were found to be consistently downregulated at both days 5 and 10 post-challenge." (PMID 37066426, 2024). "Because MYC, PML, and PHF8 have been implicated in human cancer metastasis, we investigated whether they were involved in CCL7 upregulation in OC-MQ." (PMID 34206004, 2021). "Cancer associated fibroblast (CAF) derived CCL7 promotes BrCa proliferation." (PMID 30850664, 2019). "Research indicates that cancer‐associated fibroblasts (CAFs) secrete elevated levels of CCL2, CCL5, CCL7, and CXCL16, which facilitate the migration and invasion of HCC cells." (PMID 40062588, 2025). "Seven chemokines (CCL18, CCL8, CXCL9, CXCL10, CXCL11, CCL26, and CCL7) showed positive relations in more than 25 cancer types." (PMID 38655053, 2024). "In CRC, Snail-expressing cancer-associated fibroblasts (CAFs) showed different cytokines secretion profiles including CCL1, CCL7, and CXCL1 when compared to normal fibroblasts affecting CRC cell migration." (PMID 38935747, 2024). "Among the identified biomarkers, Ccl7 emerged as a hub gene with broad implications in inflammatory diseases and cancer." (PMID 39902039, 2024). "Meanwhile, CCL7 has been shown to enhance both cancer progression and metastasis via EMT, including in CRC cells." (PMID 37446056, 2023). "High CCL7 expression has been reported in NSCLC and linked to malignant phenotypes including the mobility and metastasis of cancer cells." (PMID 36118415, 2022). "Further studies are needed to elucidate the exact factor derived from cancer cells for CCL7 induction in macrophages." (PMID 34206004, 2021). "Clinical studies have linked MCP-3/CCL7 overexpression with liver metastasis, while cell culture studies have demonstrated MCP-3 to promote cancer cell proliferation in addition to enhancing their migratory and invasive properties." (PMID 34884259, 2021). "It is reported that CCR1, CCR2, CCR3 and CCR5 are involved in CCL7‐mediated macrophage migration and contribute to various inflammatory diseases and cancer." (PMID 34189838, 2021). "Studies have shown that CCL7 promotes migration and invasion of cancer cells in a dose-dependent manner." (PMID 31400751, 2019).
cancer (continued). "Enhanced expression of CCL7 increases macrophage chemotaxis potential, which is proven to promote cancer initiation and malignant progression." (PMID 29915688, 2018). "The preferential replication of this virus in cancer cells makes it possible to target recombinant MVMp/CCL7 parvoviruses to cancer cells." (PMID 29915688, 2018). "More recently, the autocrine and paracrine roles of CCL7 in cancer progression have received increasing attention, although the potential molecular cues involved are incompletely understood." (PMID 29915688, 2018). "CCL7 secretion is increased after IL-1β produced by cancer cells activates the NF-κB signaling pathway in cancer-associated fibroblasts (CAFs)." (PMID 29915688, 2018). "Using combined in vitro and in vivo approaches, we demonstrate here that the ability of PPAT to attract cancer cells away from the prostate gland is dependent on an original CCR3/CCL7 axis." (PMID 26756352, 2016). "Our results revealed that CCL7 overexpression indeed correlated with cancer cell tumorigenesis and metastasis." (PMID 27167205, 2016). "Chemokine ligand 7 (CCL7) enhances cancer progression and metastasis via epithelial-mesenchymal transition (EMT)." (PMID 27167205, 2016). "Additionally, mature adipocytes can secrete CC-chemokine ligand 7 (CCL7), which directly promotes cancer cell migration by interacting with the CC-chemokine receptor 3 (CCR3) on PCa cells." (PMID 40703555, 2025). "In the osteoblasts_Gapd2 subpopulation, pathways such as proteoglycans in cancer (Col1a1, Col1a2, Hcls1, Hif1a, Stat3, Vav1), IL-17 signaling (Mmp13, Mmp3, S100a9, Ccl7, Cebpb), and ECM–receptor interaction (Col11a2, Col1a1, Ibsp, and Tnn) were activated (p < 0.05)." (PMID 41459160, 2025). "Given the broad involvement of Ccl7 in inflammatory diseases and cancer, targeting Ccl7 could have significant therapeutic potential." (PMID 39902039, 2024). "In addition to CCL2, three other MCP chemokines exist—CCL7 (MCP-3), CCL8 (MCP-2), and CCL13 (MCP-4)—and are implicated in cancer progression." (PMID 39409924, 2024). "Cross‐linking immunoprecipitation sequencing (CLIP‐seq) analysis shows the direct association of FMRP with Ccl7 mRNA, implying that FMRP depletion may abolish the inhibition of Ccl7 translation in cancer cells, which in turn directly activate CD8 T cells." (PMID 36968189, 2023). "Contrastingly, Aldh1a3, Ccl5, Ccl11 and Ccl7 expression were significantly higher in ALDH+ BCSCs (P2) as compared to bulk cancer cells (P0), indicating that our sorted populations were indeed pure and RNA sequencing was reflecting the expected characteristics of these BCSC populations." (PMID 35053617, 2022). "Individual miRNAs can regulate multiple target genes; several miR-23b target genes, such as autophagy-related gene 12 (ATG12), chemokine ligand 7 (CCL7), and E-cadherin, have been identified and validated and play significant roles in inflammatory and cancer-related pathways." (PMID 31780861, 2019). "So far, only a few studies have focused on deciphering the role of CCL7 in cancer development." (PMID 30764543, 2019). "Notably, several of the cytokines whose expression was upregulated in parenchymal cancer cells (e.g. CCL2, CCL7, CXCL1, CXCL2, CXCL5, CCL20) have been implicated in the attraction of immune cells." (PMID 27203741, 2016). "Similarly, in the group without T2D, MCP-3 (also known as C–C motif chemokine 7 [CCL7]) showed a significant association with cancer-related mortality and a borderline significant association with cardiovascular mortality." (PMID 39334377, 2024). "In particular, this study shows that SCs-derived CCL7 binds to its receptor CCR2 in cancer cells to upregulate the expression of the EMT-related factor TIMP1, while TIMP1 binds to CD63 to enhance the expression of CCL7 in SCs." (PMID 40037534, 2025).
cancer (continued). "Chemokines CCL7, CCL24, and CXCL13, as well as IL-10 and Bmp2, exert pro-tumorigenic effects in a variety of cancers, promoting the invasiveness, metastasis, and stemness of cancer cells." (PMID 38892209, 2024). "Among the upregulated ligands in the scRNA‐seq dataset, only C‐C motif chemokine ligand 7 (CCL7) was remarkably upregulated in both mRNA and secreted protein in cultured FMRP‐KO cancer cells." (PMID 36968189, 2023). "In particular, chemokines, including CXCL8, CXCL10, CXCL11, CXCL16, CCL26, and CCL7, as well as chemokine receptors, including CXCR3, CCR2, CCR5, and CCR1, were positively correlated with MRPL13 expression in various cancer types." (PMID 37827692, 2023). "Artificial up- or downregulation of CCL7 was induced in LUAD cells to explore its function in the mobility, EMT of cancer cells, and migration of M2 macrophages." (PMID 36118415, 2022). "The previous findings and our current data suggest that some soluble factors from cancer cells can activate the p38/JNK pathway, resulting in CCL7 overexpression via transcriptional regulation by PHF8 in macrophages." (PMID 34206004, 2021). "Let-7d directly targets c-Myc, HMGA2, CCL7, PBX3 and COL3A1, and so inhibits thereby inhibiting cancer cell invasion and metastasis." (PMID 33507713, 2021). "The role of MCP-2/CCL8 and MCP-3/CCL7 in colorectal carcinogenesis and cancer progression is less studied and clear." (PMID 34884259, 2021). "The discussed group of CC chemokines (CCL2, CCL7, CCL8, and CCL13) have numerous pro-cancer functions, which outweigh their anti-cancer properties." (PMID 33182504, 2020). "It is also noteworthy that, compared to ASCs-CM, hUCESCs-CM contain lower levels of factors known to participate in cancer progression, such as EGFR, FGF 4 and 9, ICAM3, IL6, IL6R, MCP3 (CCL7), MIF, sgp130 and VEGFD." (PMID 25296979, 2014). "Additionally, our analysis of chemokines revealed a strong positive correlation between EXO1 expression and CCL7, CCL13, and CCL18 in BRCA, OV, THCA, and UCEC, while a negative correlation was observed with CCL14 and CCL16 in most female-related cancers." (PMID 40433389, 2025). "CCL7, CCL23, and IL-32 attract monocytes and macrophages to regulate cancer antigen presentation." (PMID 39235457, 2024). "Along with CCL7, which is downregulated 2-fold in our hPARG-expressing cells, CCL2 activates the CCR2 receptor (C-C Motif Chemokine Receptor Type 2) pathway, which expression in cancer cells have been demonstrated to promote immune suppression." (PMID 35585513, 2022). "Cancer cells (i.e., CNA+) from the prepuberty disease state had significant high expression of genes involved in the innate immunity and chemokine signaling pathway (Ccl2, Ltf, Ccl7, Ccl20)." (PMID 35851387, 2022). "Both A-MQ and O-MQ produced higher amounts of CCL7 than macrophages without cancer cell stimulation." (PMID 34206004, 2021). "The expression of CCL2, CCL7, and CCL8 in CAF is very important in cancer." (PMID 33182504, 2020). "Due to the recruitment of monocytes, CCL2, CCL7, CCL8, and CCL13 are important in the pathogenesis of many diseases where an important role is played by monocytes and macrophages, in particular atherosclerosis, inflammatory bowel disease, and cancer." (PMID 33182504, 2020). "Among the remaining 8 DEGs (ADRA2A, P2RX6, XCL2, XCL1, CCL7, TRIM54, TNFRSF18 and SPOCK1), the expression of ADRA2A, the top one, in KIRC based on individual cancer is lower than the normal tissues, but patients with lower expressed ADRA2A have a better overall survival (OS)." (PMID 31159832, 2019). "Thus, chemokine CCL7 may act as a strong attractant for immunocompetent cells to strengthen the immune response, and it might be expected to serve as important adjuvants in cancer vaccines or considered for the treatment of certain human cancers by direct intratumoral application in the near future." (PMID 29915688, 2018). "CCL7 and CXCR4 are well known chemokines that promote cancer progression." (PMID 29890660, 2018).